APOBEC3B (apolipoprotein B mRNA editing enzyme catalytic subunit 3B)
Diseases named in the same sentence as APOBEC3B in open-access papers (continued):
Sharing a sentence is not in itself a finding about the gene and the disease.
ovarian carcinoma (continued). "APOBEC3B is overexpressed in ovarian cancer cell lines and high-grade primary ovarian cancers." (PMID 32934779, 2020). "In the present study, we investigated the tumorigenic role of APOBEC3B in ovarian cancer." (PMID 29853799, 2018). "Western blotting and SRB assay were performed to explore the role of APOBEC3B in ovarian cancer." (PMID 29853799, 2018). "As APOBEC3B has been indicated in cancer progression, we then observed whether APOBEC3B promoted cell viability of human ovarian cancer cells." (PMID 29853799, 2018). "Therefore, future studies with adequate sample size are needed to understand the role of APOBEC3B in ovarian cancer progression." (PMID 29853799, 2018). "Knockdown of APOBEC3B expression affects ovarian cancer viability." (PMID 29853799, 2018). "APOBEC3B expression is an independent prognostic factor in ovarian cancer patients." (PMID 29853799, 2018). "Unlike a previous study which reported that APOBEC3B protein predominantly localized to the nuclear compartment in ovarian cancer cell lines, our immunostaining data from ovarian cancer tissues showed that APOBEC3B localized in both nuclear and cytoplasmic compartment." (PMID 29853799, 2018). "Four ovarian cancer cell lines with different endogenous expression of APOBEC3B were chosen." (PMID 29853799, 2018). "In addition, ovarian cancer cell lines were transfected with APOBEC3B siRNA or pLenti-APOBEC3B construct." (PMID 29853799, 2018). "Taken together, our study indicated that APOBEC3B expression may play an important role in viability and survival of ovarian cancer." (PMID 29853799, 2018). "In addition, the in vitro data from our study showed that knockdown of APOBEC3B expression affected ovarian cancer cell viability." (PMID 29853799, 2018). "The APOBEC3B deletion also does not show association with ovarian cancer in either GDANSK [OR(95%CI)=0.77(0.50-1.19), p=0.24] or VILNIUS [OR(95%CI)=0.66(0.27-1.61), p=0.36]." (PMID 29100317, 2017). "Small molecules as agonists or antagonists, which are able to modulate specifically the APOBEC3G and APOBEC3B levels and activities, respectively, can be as well considered as starting points for further development of combinatorial drug applications in ovarian cancer." (PMID 27527602, 2016). "Therefore, APOBEC3B is a potential therapeutic target which may contribute to the development of new ovarian cancer treatment strategies." (PMID 29853799, 2018). "However, the clinical relevance of APOBEC3B in ovarian cancer needs to be further investigated." (PMID 29853799, 2018). "Our study results showed that APOBEC3B expression was one of the independent prognostic factors to predict OS and DFS of ovarian cancer patients." (PMID 29853799, 2018).
gastric cancer (8 papers, 2018 to 2024). A primary or metastatic malignant neoplasm involving the stomach. "APOBEC3s are immunosuppressive in some cancers, and higher APOBEC3B expression has been associated with less immune cell infiltration in adrenocortical carcinoma and gastric cancer." (PMID 36978147, 2023). "APOBEC3B downregulation with shRNA resulted in enhanced cytotoxicity of PDCD2 (programmed cell death protein 2) in gastric cancer cell line MKN28, probably due to the lower mutational load and noninterfered transcription of this tumour suppressor gene." (PMID 37568604, 2023). "Higher expression patterns in mRNA and protein levels of APOBEC3B were also found in gastric cancer tumour samples compared to paired normal tissue samples in a cohort of 236 patients." (PMID 37568604, 2023). "In accordance with this model, studies in adrenocortical carcinoma and gastric cancer—which both show immunosuppression with APOBEC3s—have found that higher APOBEC3B expression is correlated with shorter survival." (PMID 36978147, 2023). "In particular, APOBEC3B high CD8+ T cell high gastric cancer patients were more likely to benefit from adjuvant chemotherapy (ACT) and PD-1 blockade." (PMID 36245972, 2022). "As expected, expression levels of AICDA, NFκB p65, CBFβ, APOBEC3A, and APOBEC3B were increased in gastric cancers with higher TNM stage." (PMID 30514953, 2018). "APOBEC3B expression levels were associated with APOBEC mutational signatures, whereas APOBEC3C expression levels were associated with decreased APOBEC mutational signatures in gastric cancer." (PMID 37568604, 2023). "For example, Xia and colleagues reported that APOBEC3B upregulation predicts immune inactivation and worse survival in gastric cancer 56, while Serebrenik and colleagues reported that APOBEC3B is overexpressed in a subset of clear cell ovarian cancer and correlates with improved clinical outcomes." (PMID 35673559, 2022). "APOBEC3s can also inhibit cell death via multiple mechanisms: APOBEC3G was shown to inhibit anoikis via Akt activation in pancreatic cancer, and APOBEC3B may decrease cell death in gastric cancer by inhibiting PDCD2 function and lowering ATM and Chk1/2 activity." (PMID 36978147, 2023). "In gastric cancers, mRNA expression levels of AICDA, NFκB p65, CBFβ, APOBEC3A, and APOBEC3B were markedly increased, similar to their expression profiles in gastric mucosae with H, pylori infection." (PMID 30514953, 2018). "In 32 gastric cancers from TCGA datasets, cases with APOBEC3B and/or AICDA expression without NKX6.3 expression showed significantly higher number of mutations than those with NKX6.3 expression." (PMID 30514953, 2018). "Results showed that expression levels of NKX6.3, CDH1, CDKN1A, and EP300 were decreased while expression levels of NFκB p65, AICDA, CBFβ, APOBEC3A, APOBEC3B, RhoA, ROCK1, ROCK2, PIK3CA, and CCND1 were increased in CagA positive gastric cancers compared to those in CagA negative cases." (PMID 30514953, 2018).
non-small cell lung carcinoma (8 papers, 2014 to 2025). A group of at least three distinct histological types of lung cancer, including non-small cell squamous cell carcinoma, adenocarcinoma, and large cell carcinoma. "It was shown that APOBEC3B upregulation is significantly associated with immune gene expression, including PD-L1 expression and T-cell infiltration in non-small cell lung cancer (NSCLC)." (PMID 41373684, 2025). "From searching the existing studies, we found that APOBEC3B overexpression could act as a promising signature in predicting the ICB responsiveness of non-small cell lung cancer (NSCLC)." (PMID 34745121, 2021). "In the present study, APOBEC3B mRNA expression was investigated using quantitative reverse transcription-polymerase chain reaction (RT-qPCR) assay using LightCycler in surgically treated non-small-cell lung cancer (NSCLC) cases." (PMID 24748981, 2014).
head and neck squamous cell carcinoma (6 papers, 2015 to 2025). A squamous cell carcinoma that arises from any of the following anatomic sites: lip and oral cavity, nasal cavity, paranasal sinuses, pharynx, larynx, and salivary glands. "The enzymatic activity of APOBEC3B (A3B) has been implicated as a prime source of mutagenesis in head and neck squamous cell carcinoma (HNSCC)." (PMID 36766673, 2023). "For head and neck squamous cell carcinomas (HNSCCs) it has been shown by Henderson and colleagues that HPV+ compared to HPV− tumors have elevated APOBEC3B and that PIK3CA helical domain mutations are APOBEC-driven in multiple cancers, including HPV+ HNSCC." (PMID 26097867, 2015).
lung adenocarcinoma (6 papers, 2015 to 2025). A carcinoma that arises from the lung and is characterized by the presence of malignant glandular epithelial cells. "Additionally, IFN-γ has been implicated as a driver of APOBEC3B expression in bladder tumors and lung adenocarcinoma." (PMID 36978147, 2023). "Using data from The Cancer Genome Atlas (TCGA), we show that FHIT-low/APOBEC3B-high expressing lung adenocarcinomas display significantly increased numbers of APOBEC signature mutations." (PMID 25401976, 2015). "APOBEC3B is generally expressed at higher levels than other APOBEC3 family members, and an analysis of multiple cancers detected enrichment of APOBEC3B in eight tumor types: bladder, breast, head and neck, lung adenocarcinoma, lung squamous cell carcinoma, prostate, clear cell renal, and uterine." (PMID 36978147, 2023). "In this regard, APOBEC3B (but not APOBEC3A) expression has been recently positively associated with interferon inducible genes expression in lung adenocarcinoma." (PMID 33049910, 2020).
myeloma (6 papers, 2018 to 2025). "In this study, we examined the significance and clinical impact of APOBEC3B (A3B) activity in multiple myeloma." (PMID 31073151, 2019). "Increased expression and activity of both APOBEC3A and APOBEC3B were also reported in multiple myeloma patients, most commonly in those with the t(14:16) translocation, which was associated with poor survival." (PMID 29642934, 2018). "APOBEC3B expression in G2/M-phase is not unique to epithelial cells either; it has also been documented in myeloma cells and in B-cells from healthy bone marrow." (PMID 39548236, 2025).
glioma (5 papers, 2018 to 2022). A benign or malignant brain and spinal cord tumor that arises from glial cells (astrocytes, oligodendrocytes, ependymal cells). "Such expression levels were consistent with earlier studies, which had reported low levels of APOBEC3B in lower-grade glioma TCGA patient samples and had suggested that mutation processes in glioma tumors could be caused by mechanisms other than APOBEC mutagenesis." (PMID 29642934, 2018). "For example, higher level of expression of APOBEC3B in glioma was correlated with increased sensitivity to an HSP90 inhibitor AUY922 (ρ = − 0.556, padj = 0.0701, n = 44, Ntests = 26,610; data not shown)." (PMID 29642934, 2018). "Expression of APOBEC3B was significantly negatively correlated with FHIT expression in glioma cell lines (ρ = − 0.407, padj = 0.0022, n = 79, Ntests = 230)." (PMID 29642934, 2018). "On the one hand, we found that these genes can be clustered into eight clusters, among which APOBEC3A and APOBEC3B were isolated separately, demonstrating that different members may have different biological functions in low-grade gliomas." (PMID 34638749, 2021). "However, this did not appear to be the case because in our analysis of glioma cell lines, which included astrocytoma, lower-grade glioma, and glioblastoma multiforme cell lines, mean APOBEC3B and FHIT expression levels were comparable to those in the pan-cancer dataset." (PMID 29642934, 2018).
head and neck cancer (5 papers, 2015 to 2022). A primary or metastatic malignant neoplasm affecting the head and neck. "In support of this idea, recent studies on head/neck cancer have linked human papilloma virus infection to APOBEC3B upregulation, and one has shown that the viral E6 oncoprotein is sufficient to trigger APOBEC3B upregulation." (PMID 25848704, 2015). "Nearly all cervical and a growing proportion of head and neck carcinomas are caused by the similar small double-stranded DNA (dsDNA) virus HPV and exhibit high APOBEC3B expression and a dominant proportion of APOBEC signature mutations (9, 11, 39, –, 41)." (PMID 28049147, 2017). "Therefore, both high levels of APOBEC3B and APOBEC3A and low levels of FHIT expression may influence APOBEC mutagenesis in the head and neck cancer." (PMID 29642934, 2018).
lymphoma (5 papers, 2014 to 2023). A malignant (clonal) proliferation of B- lymphocytes or T- lymphocytes which involves the lymph nodes, bone marrow and/or extranodal sites. "Overexpression of APOBEC3B in a APOBEC3B low expressing lymphoma cell line induced accumulation of dC>dT mutation within the c-myc gene." (PMID 26097867, 2015). "APOBEC3B was shown to be upregulated in several human lymphoma cell lines where cells with high APOBEC3B expression possessed mutations, mainly dC>dT transitions, in actively transcribed oncogenes." (PMID 26097867, 2015). "Analysis of the Brune lymphoma dataset in the Oncomine database revealed that the APOBEC3A mRNA level in DLBCL was similar to whereas the APOBEC3B mRNA level was higher than that in normal tissue." (PMID 35592333, 2022). "We also found that APOBEC3B was more highly expressed than APOBEC3A in DLBCL tissues in both the Brune and Compagno lymphoma datasets." (PMID 35592333, 2022). "Although more research is needed, we speculate that whereas replication stress-induced APOBEC3B regulation could contribute to a portion of APOBEC3-mediated mutagenesis, APOBEC3G upregulation could enhance DNA repair, as has been previously postulated in lymphoma cells." (PMID 27634334, 2016). "Similar trends in APOBEC3B and APOBEC3A expression in DLBCL were observed in The Cancer Genome Atlas (TCGA)-based GEPIA database (data not shown), but not in the Compagno lymphoma DLBCL dataset of TCGA." (PMID 35592333, 2022).
asthma (4 papers, 2020 to 2023). "A suggestive association was found for the SNP rs5995653 from the intergenic region APOBEC3B-APOBEC3C, which showed evidence of replication in 1697 European children with asthma (OR for the A allele: 0.76, 95% CI: 0.62–0.93, p-value = 7.52 × 10−3)." (PMID 32326339, 2020). "In another ICS response study in admixed children from GALAII and SAGE cohorts with asthma, rs5995653 SNP related to apolipoprotein B mRNA-editing catalytic polypeptide 3 (APOBEC3)B and APOBEC3C genes was associated with a protective effect against asthma exacerbations." (PMID 37228580, 2023). "APOBEC3B and APOBEC3C, genes that have not been previously associated with asthma, encode subunits of a cytidine deaminase, a protein with an RNA editing function that has an important role in the immune response to several viruses by restricting their replication." (PMID 32326339, 2020).
bladder tumor (4 papers, 2018 to 2025). "To determine whether APOBEC3A or APOBEC3B was the predominant deaminase, we compared our BKPyV infection models of urothelial carcinogenesis and patient bladder tumor data to a Hap1 cell line model [with overexpression of APOBEC3A or APOBEC3B in isolation]." (PMID 41337590, 2025).
HIV-1 infection (4 papers, 2005 to 2018). The type species of lentivirus and the etiologic agent of acquired immunodeficiency syndrome (AIDS). "Previously, two independent groups reported conflicting conclusions regarding the impact of the APOBEC3B gene deletion on human HIV-1 infection in vivo, and this issue remains unclear." (PMID 24667791, 2014). "Therefore, to determine the effects of different APOBEC3B genotypes on HIV-1 infection in vivo and in vitro, we investigated the frequencies of intact and deletion polymorphisms of the APOBEC3B gene in a matched cohort in Japan." (PMID 24667791, 2014). "Therefore, it was necessary to verify the effects of APOBEC3B on HIV-1 infection in vivo." (PMID 24667791, 2014). "APOBEC3B is able to suppress the infectivity of HIV-1, while stimulation of TNFSF4 (tumor necrosis factor receptor superfamily, member 4) by its ligand enhances HIV-1 infection." (PMID 17014716, 2006). "Importantly, APOBEC3B (A3B) is constitutively localized in the nucleus and inhibits HIV-1 infection independent of the presence of Vif, which otherwise counteracts the activity of the remaining A3 family members." (PMID 30233553, 2018). "Likewise, Yu and colleagues have recently reported that human APOBEC3B and APOBEC3C can inhibit SIV but not HIV-1 infection of human cells." (PMID 15998449, 2005).
melanoma (4 papers, 2018 to 2023). A malignant, usually aggressive tumor composed of atypical, neoplastic melanocytes. "Nuclear APOBEC3B (A3B) upregulation characterizes head/neck mucosal melanomas, fuels mutational load, and promotes inter‐ and intratumoral heterogeneity." (PMID 36416305, 2023). "Here, we show that overexpression of APOBEC3B in tumors increases resistance to chemotherapy, but simultaneously heightens sensitivity to immune checkpoint blockade in a murine model of melanoma." (PMID 32034147, 2020). "Among the cancer categories with ≥ 5 cell lines, these included acute myeloid leukemia (LAML; mean APOBEC3B expression of 9.44) and melanoma (MEL; 9.81)." (PMID 29642934, 2018).
metastatic tumors (4 papers, 2016 to 2023). "Both primary and metastatic tumors exhibit increased frequencies of C-to-T mutations in TC dinucleotide motifs consistent with the established biochemical activity of APOBEC3B." (PMID 36865194, 2023). "Since APOBEC3B is a gain-of-function mutagenic enzyme, it may be treatable with small molecules, which could have an important role in the management of metastatic disease." (PMID 28141868, 2017).
prostate carcinoma (4 papers, 2016 to 2023). A carcinoma that arises from epithelial cells of the prostate gland. "These include APOBEC3B proteins which are a source of genome wide mutations and can lead to an increased risk of several cancers including prostate cancer." (PMID 28811834, 2017). "Interestingly, the APOBEC3B mutation signature was detectable in colorectal and prostate cancers only when whole- genome, but not whole-exome, data were used, suggesting a tissue-specific bias against enrichment of mutations by APOBEC3B in coding regions." (PMID 26920143, 2016). "The dysregulation of HERV activation restriction genes has also been found in other cancers, such as the overexpression of TET1, TET3, and APOBEC3B but downregulation of APOBEC3C, 3G, 3D, 3H, and C2 in prostate cancer, and different cancers may involve different activation restriction genes." (PMID 37509325, 2023).
adrenocortical carcinoma (3 papers, 2020 to 2023). "However, the role of APOBEC3B in adrenocortical carcinoma (ACC) and the mechanisms through which its expression is regulated in cancer are not fully understood." (PMID 32934779, 2020).
COVID-19 (3 papers, 2022 to 2024). A disease caused by infection with severe acute respiratory syndrome coronavirus 2. "We found a high expression of APOBEC3A, APOBEC3B, APOBEC3C, APOBEC3D, APOBEC3F, APOBEC3G and APOBEC3H in the classical, intermediate monocytes and NK cells of the COVID-19 patients compared to the healthy or recovered individuals." (PMID 36532041, 2022). "Genes in this pathway, AICDA, CDADC1, CDA and APOBEC3D, were regulated in opposite directions (only AICDA was statistically significantly downregulated in SLE and CDA up in COVID-19), while APOBEC3A and APOBEC3B were significantly upregulated in COVID-19, but not SLE." (PMID 38302132, 2024).